IFIH1 (interferon induced with helicase C domain 1)
Diseases named in the same sentence as IFIH1 in open-access papers (continued):
Sharing a sentence is not in itself a finding about the gene and the disease.
infection (continued). "These include Ifi27, Ifih1, Irf7 and Oas1b which were upregulated at 72 hr and 96 hr post infection except Becn1 that was over-expressed only at 72 hr post infection, and Spn which was over-expressed at all time points." (PMID 18558011, 2008). "Expression of IFIH1 gene increases with increasing infection intensity." (PMID 40963624, 2025). "Notably, activated MG 1 was the primary cell type expressing genes encoding RIG-I (Ddx58) and MDA5 (Ifih1), PRRs important in alphavirus sensing, along with type I IFN genes Ifnb1 and Ifna2 throughout infection." (PMID 39749347, 2024). "In the IFE cells, infection was associated with the upregulation of interferon regulatory and inducible genes (IRF, IRF9, IFIT5, IFIH1), while a downregulation of IFI35 and IFI6 was observed, potentially indicating a mechanism to prevent excessive immune activation." (PMID 38743760, 2024). "During E30 infection, genes associated with the type I IFN signaling pathway (Isg15, Mx1, Mx2, Sp100, Ifit1, Ifit3, Ifih1, Irf7, Irf9, guanylate-binding proteins 2 [Gbp2], and Stat1) and defense response to viruses (Ddx58, Ddx60, Zbp1, Oas2, Nlrc5, and Eif2ak2) were significantly upregulated." (PMID 36147849, 2022). "To identify potential cytokine‐production patterns in WT and KO mice in response to N67C or YM infection, we infected WT, Ifih1–/–, Mavs–/–, Mb21d1–/–, and Tmem173gt mice with either N67C or YM, then examined the serum amounts of IFN‐α, IFN‐β, and IL‐6 during the course of each infection." (PMID 35635376, 2022). "The transcription of IFIH1 was retained in both acute and slow infection." (PMID 32664675, 2020). "In addition, six genes (SLFN12, MX2, TRIM30A, GBP1, GBP6, and IFIH1) were common to 15 dpi and the early infection period." (PMID 29147886, 2018). "In this study, the associated genes (IFIH1, IFNB1, DDX58, CXCL10 and IL12A) in the RIG-I-like receptor signaling pathway were increased obviously at 8 h post-infection(p<0.05), compared to 3 h post-infection." (PMID 28938587, 2017). "For example Oas1b, Ifi27, Ifih1 and Irf7 genes were up-regulated at 72 and 96 hr post infection." (PMID 18558011, 2008). "Protein–protein interaction network analysis identified several hub genes (Usp18, Stat2, Ifih1, Jun, Irf7, Rsad2, Ifit1, Mx1) that likely play central roles in coordinating the antiviral immune response and immunometabolic regulation across different phases of infection." (PMID 40867782, 2025). "The partial loss of Ifih1 gene expression altered IFN-β production levels and regulatory T-cell (Treg) responses after CVB4 infection, suggesting that altering Ifih1 expression regulates the autoreactive component of the host response to infection that protects against the onset of VID." (PMID 32727064, 2020). "Interestingly, two cytosolic PRRs―TLR3 and IFIH1, whose proteins products are involved with the detection of viral PAMPs, such as reoviral double-stranded RNA―were upregulated at the 6 h time point post-infection." (PMID 22455317, 2012). "Similar results were observed with the virulent strain used in our study (26544/OG10), where expression levels for some key antiviral genes (DDX58, DHX58, IFIH1, MX1, and OAS2) decreased slightly as infection progressed." (PMID 40530033, 2025). "To confirm these results, we stably knocked-down the expression of RIG1, IFIH1 and MAVS with shRNAs by lentiviral infection." (PMID 38383514, 2024). "We identified important genes DE in both our in vitro and in vivo infection models consistent with previous studies, namely, TLR3, IFIH1 (MDA5), SOCS1, OASL, DDX60, STAT1, MX1, CMPK2, LY96 (MD-2), STAT1, STAT2, TRIM25, IRF7, and IFIT5." (PMID 38675946, 2024). "Our results showed that the expression levels of TLR3, IFIH1, and IRF7 were increased after infection in resistant chickens; and expression levels of IRF7 were higher in resistant H5N1-infected chickens than in susceptible H5N1-infected Ri chickens." (PMID 34991196, 2022).
infection (continued). "We showed that cytosolic nucleic acid signaling pathway-related proteins such as IFIH1 (MDA5), ISG15, IFI202 and IFI204 were significantly upregulated in the M28ΔtatA/M28 infection group." (PMID 34195100, 2021). "In the presence of HO infection, the stimulatory effect of IFNT on expression of GBP4, ISG15, HERC5, RSAD2, IFIH1, IFIT3, and MX1 was significantly reduced (IFNT vs. IFNT+HO, P < 0.05–0.01)." (PMID 33898551, 2021). "ISGs and immune response genes such as IFIT1, IFIT2, IFIH1, MX1, MX2, and RSAD2 were highly down-regulated in response to all viruses at later time points of infection, confirming our transcriptome data." (PMID 33791243, 2021). "Upon fetal infection, a set of core responsive IFN-inducible genes (CXCL10, IFIH1, IFIT1, IFIT3, ISG15, and MX1) were strongly upregulated in both tissues." (PMID 33148169, 2020). "When normalized against the whole LFRT of uninfected mice, expression of Ddx58 (RIG-I) and Ifih1 (MDA5) is similar in all compartments and these genes are minimally induced upon infection." (PMID 31554802, 2019). "More importantly, the silencing of SNRNP200 in MDM decreases the induction of IFIH1 and IFIT1, and completely blocks IRF3 Ser386 phosphorylation within 3 hours post-infection." (PMID 27454487, 2016). "For instance, IBV 2575 AT infection activated multiple PRR genes, including IFIH1, TLR1LA, TLR2-2, TLR3, TLR4, TLR7, and TLR15." (PMID 27876864, 2016). "The influence of the immunity (and thus of IFIH1) on enterovirus replicating in the gut may be indeed less pronounced than in the blood – it is assumed that the antibodies can prevent spreading of the infection from the gut, but cannot provide “sterilizing immunity”." (PMID 23144876, 2012). "We found that, in addition to a broad induction of ISGs (for example, DTX3L, OAS3, RTP4, IRF7, MX2, IFIT3, IFIH1), only IFNB1 and, more robustly, IFNL1-like and IFNL3-like were induced in virus-infected organoids at 1 and 3 days after infection compared to the uninfected controls." (PMID 40399606, 2025). "Thus, the expression levels of DDX58, DHX58, IFIH1, MX1, and OAS2 decreased slightly as infection with 26544/OG10 progressed (higher fold-changes at 3 hpi compared to 21 hpi)." (PMID 40530033, 2025). "Likewise, the most abundant group of upregulated genes after infection with swH1N1 was ISGs or genes involved in their activation (DDX58 (RIG-I), ZBP1, IFIH1 (MDA5), IRF7, and DDX60)." (PMID 39247193, 2024). "These variants were found in inflammasome genes (NLRP1/3 and CASP1), genes mediating inflammasome inactivation via auto- and mitophagy (RIPK2 and MEFV), and genes involved in the response to infection with DNA viruses (POLR3A, DHX58, and IFIH1) and type-1 interferons (TYK2 and PTPRC)." (PMID 37626706, 2023). "In VACV∆C7L-infected Ifih1−/−Sting1gt/gt mice, we observed infectious virions persisted in monocytes from Ifih1−/−Sting1gt/gt mice at day 5 post-infection with VACV∆C7L but were cleared in Lyve1− IMs despite of lacking MDA5 and STING." (PMID 35351885, 2022). "For example, heat-iMVA infection triggered higher levels of IFN-inducible genes than MVA, including Ifih1 (MDA5), Ddx58 (RIG-1), Oasl2, Oas3, TLR3, Nod1, Ifna4, Ifnb1, Ccl5, Cxcl9, Cxcl10, and members of the guanylate binding protein (Gbp) family, as largely dependent on STING (marked as b)." (PMID 36261460, 2022). "We observed a temporal increase in expression of the Type I IFN response genes Il1rn, Ifit2, Ifit1 and Ifih1 (data not shown) upon infection." (PMID 34603294, 2021). "Most of the upregulated proteins, including DHX58, IFIH1, and IFI204, belong to the functional category of cytosolic nucleic acid sensing receptors, suggesting the importance of this class in recognizing Tat mutant infection." (PMID 34195100, 2021).
infection (continued). "The IFNT induced expression of TRIM56, DDX58, and IFIH1 was further enhanced in the cells infected with KY (IFNT vs. IFNT+KY, P < 0.05–0.01) and that of TRIM56 and IFI27 was further increased in the presence of HO infection (IFNT vs. IFNT+HO, P < 0.05)." (PMID 33898551, 2021). "Previous research has shown that infection with coronaviruses activates an innate immune response upon sensing of viral RNA by interferon-induced with helicase C domain 1 (IFIH1), also known as MDA5." (PMID 32574256, 2020). "Our main findings were: 1) the host immune response was initiated only in fetuses with detectable levels of PRRSV; 2) upon infection of fetal thymus, a set of core responsive IFN-inducible genes (CXCL10, IFIH1, IFIT1, IFIT3, ISG15, and MX1) were strongly upregulated in both tissues." (PMID 33148169, 2020). "These variants were found in inflammasome genes (NLRP1/3, CASP1), genes mediating inflammasome inactivation via auto and mitophagy (RIPK2, MEFV), and genes involved in response to infection with DNA viruses (POLR3A, DHX58, IFIH1) and to type-1 interferons (TYK2, PTPRC)." (PMID 31235738, 2019). "A comparison of expression after WNV infection to expression in subsets from uninfected mice revealed that as, expected, both Ddx58 and Ifih1 expression increased to varying degrees in several myeloid subsets after infection, but MAVS gene expression did not." (PMID 29408905, 2018). "To test whether the nucleic acid-sensing pathways have a function in host defense against VACV∆C7L infection, we performed intranasal infection of VACV∆C7L in cGas−/−, Sting1gt/gt (which lack functional STING), Ifih1−/− (MDA5 knockout), Ifih1−/−Sting1gt/gt or Irf3−/− mice." (PMID 35351885, 2022). "At the transcriptome level, the high expression levels of viral sensors MDA5 (IFIH1), R1G-1 (DDX58), and ISGS (ISG15, Mx1, Mx2, RSAD2, IFIT3, and IFIT5) and transcription factors like IRF-7 and STAT-1 that induce ISG expression were found in lymphocytes during virulent PPRV infection." (PMID 34631844, 2021). "However, upon infection with the Sendai virus (SeV), the cells exhibited increased expression of IFN and chemokine genes (IFNB1, IL29, IL28A, IL28B and CXCL11) and interferon-stimulated genes (DDX58, IFIH1, DHX58, IFIT1-3, and OASL)." (PMID 20661427, 2010). "Expression of eight of these genes (IFIH1, OAS2, IFIT1, IFIT2, IFIT3, IFIT5, USP18 and DDX58F) was significantly elevated in response to VSV-ΔM51 infection in permissive cells, but not in resistant PDACs." (PMID 27533247, 2016). "At the earlier time points post-infection, we did not observe any overlap with down-regulated mRNAs; however, 27 up-regulated mRNAs were common to all early treatment groups, including TLR3, IFIT5, IFIH1 (MDA5), MX1, RSAD2 (viperin), CMPK2, SOCS1, and SCNN1D." (PMID 38675946, 2024).
cancer (91 papers, 2011 to 2026). A tumor composed of atypical neoplastic, often pleomorphic cells that invade other tissues. "Similarly, IFIH1, which encodes the MDA5 viral pathogen sensor implicated in IFN and innate immune responses, has been highlighted by others as a gene whose variants can affect cancer IFN signaling and, potentially, response to immunotherapy." (PMID 37534375, 2023). "Activation of the RIG-I/IFIH1/MAVS pathway and de-repression of ERVs were observed in cancer, aging, autoimmune, and neurodegenerative diseases." (PMID 38383514, 2024). "The previously unknown risk loci are implicated in cancer development and progression (e.g. CDKL1), pigmentation (e.g. TPCN2), cardiometabolic (e.g. FADS2), and immune-regulatory pathways for innate immunity (e.g. IFIH1), and HIV-1 viral load modulation (e.g. CCR5)." (PMID 36496446, 2022). "Interferon induced with Helicase C Domain 1 (IFIH1) is a member of the IFN gamma family and has been suggested as an inducer of growth inhibition or apoptosis of multiple types of cancer cells." (PMID 34769455, 2021). "We then used the Tumor IMmune Estimation Resource (TIMER) database, which allows the analysis of immune infiltrates from RNA expression data across different cancer types, to test the influence of RSAD2 and IFIH1 on immune cell infiltration." (PMID 32978520, 2020). "Three other genes, IFIH1, MYOT and SAMD4A, that were found to be overexpressed in the Top-resistant cell lines were not previously reported to be related to drug resistance or even to any cancer." (PMID 28611294, 2017).
tumor (83 papers, 2008 to 2026). "An extended analysis of additional type I IFN inducers showed that NLRC4 expression had the highest correlation overall across the various DC subsets and tumor types, followed by IFIH1, RIGI, TMEM173, and finally ADAR." (PMID 38652550, 2024). "Of note, overexpression of TGFBI and interferon-induced proteins IFIT2, IFIH1 and IFI44L in the residual tumor were also associated with reduced RFS." (PMID 26021444, 2015). "Lastly, we sought to develop and assess a final five‐mRNA (UBE2L6, PARP14, IFIH1, IRF2, and GBP4) risk‐based model, which we hoped, could effectively predict clinical outcomes for patients as well as depict the tumor immune infiltration landscape of SKCM." (PMID 32902917, 2020). "In addition, IFIH1 is involved in enhancing natural killer cell function and may play a role in tumor cell apoptosis." (PMID 32271791, 2020). "We validated the upregulation of OAS1-3, MDA5/IFIH1, and RIG-I/DDX58 in Western blots, where astrocytes were treated with a variety of tumor cell line EVs." (PMID 39585062, 2024). "Consistent with transcriptomic and proteomic profiles, F3-8 EVs (and to some extent, F3-8 MVs/“microvesicles”) promoted expression of OAS1-3, MDA5/IFIH1, and RIG-I/DDX58, overall relative to EVs from other tumor cell lines, including G17-1 EVs." (PMID 39585062, 2024). "IFN-β can also stimulate the upregulation of IFIH1 and RIG-I, mediate innate immune response, kill tumor cells with low neurotoxicity, and therefore inhibit tumor growth." (PMID 35620480, 2022). "An interferon gene signature was also present in the profiles derived from the tumor epithelium of the ER-positive tumors (e.g., STAT1, IFIT1, IFIH1, IFI27, ISG15, OAS1, OAS3, OASL) and ER-negative tumors (e.g., HLA-DQA1 and HLA-DQB1)." (PMID 19225562, 2009). "IFIH1 and IFN-β interact to activate the body’s anti-tumor immune response." (PMID 35620480, 2022). "Activation of IFIH1 (also known as MDA5) in tumors has been identified to facilitate re‐activation of tumor‐specific T cells which are otherwise functionally defective within the TME and to impede tumor‐induced immunosuppression in an IFN‐dependent manner." (PMID 32902917, 2020).
infectious disease (7 papers, 2013 to 2025). A disorder directly resulting from the presence and activity of a microbial, viral, or parasitic agent in humans. "IFIH1 deficiency adds to an as yet short list of autosomal recessively inherited single-gene defects that predispose to infectious disease." (PMID 29018476, 2017). "Moreover, another antiviral gene, IFIH1 (interferon induced with helicase C domain 1), was significantly up-regulated in patients with T2DM and involved in all infectious disease pathways." (PMID 28427244, 2017).
Blood Cancer (1 paper, 2020). "The IFIH1 variant (2-163136505-C-G) was found in EUR PML cases for all four primary disease groups (Blood Cancer, HIV, MS, and Other) plus one AFR case (HIV)." (PMID 32256442, 2020).
IFIH1 also shares sentences with these, for which no sentence is quoted: clinically amyopathic dermatomyositis (36 papers); inflammatory myopathies (34); Skin ulcer (32); Arthritis (29); respiratory failure (18); juvenile dermatomyositis (17); polymyositis (17); vasculopathy (17); Flavivirus Infections (15); connective tissue diseases (13); lung disease (13); calcinosis (10); lung carcinoma (10); hepatoma (9); pulmonary fibrosis (9); lymphopenia (8); bacterial infection (7); dengue (7); Erythema (7); hyperferritinemia (7); macrophage activation syndrome (7); vasculitis (7); antisynthetase syndrome (6); colorectal cancer (6); immune disorders (6); polyarthritis (6); Skin rash (6); alopecia (5); Fever (5); pancreatic cancer (5).
A further 210 diseases each share a sentence with IFIH1 in 5 papers or fewer.